TP63 (tumor protein p63)
Diseases named in the same sentence as TP63 in open-access papers (continued):
Sharing a sentence is not in itself a finding about the gene and the disease.
cervical cancer (20 papers, 2010 to 2026). A primary or metastatic malignant neoplasm involving the cervix. "Previous publications show genetic variation of TP63 may influence susceptibility to lung adenocarcinoma and cancer in the Han population; substantial overexpression of TP63 was found in cervical cancer tissues." (PMID 29862288, 2018). "Recurrent HPV integrations near cancer‐related genes (such as MYC and TP63) have been previously reported in cervical cancers." (PMID 38013620, 2024). "3q28 is significant copy number gain in cervical cancer, amplification and overexpression of TP63 at 3q28 is a biomarker of progression from CIN to cervical cancer." (PMID 34676167, 2021). "Nevertheless, the ΔN/TAp63 mRNA expression ratio is a valuable concept to apply for clinical use as well as to understand the disruption of the ΔN/TAp63 mRNA expression ratio from TP63 gene in cervical cancer." (PMID 30973901, 2019). "The detection of TP63 in proliferating basal squamous cells has been noted in various cancers including breast, prostate, and cervical cancer." (PMID 25531390, 2014). "We show that human papillomavirus (HPV) integrations in cervical cancers alter host 3D chromatin contacts and cause over‐expression of genes (including MYC, TP63 and ERBB2), which are mostly confined within the topologically associating domains with integration." (PMID 38013620, 2024). "Therefore, the correlations between intronic miR-944 and its host gene, TP63 (TAp63 or ΔNp63), in cervical cancer should be investigated to better elucidate the generation of intronic miRNAs and their function in such malignancies." (PMID 32764455, 2020). "Gene analysis has identified SOX2 and TP63 gene expression as important in defining molecular subtypes in HPV related head and neck cancer and SOX2 has been associated with a number of other human cancers including cervical cancer." (PMID 25531390, 2014). "Moreover, CTA-55I10.1 shows a similar expression profile to TP63 in the Exon array data and also in cervix cancer cell line mRNA, with intact RNA." (PMID 21407225, 2011). "However, associations of miR-944 with its host gene, TP63, which encodes TAp63 and ΔNp63, in cervical cancer have not been fully investigated." (PMID 32764455, 2020). "Therefore, it was hypothesized that miR-944 may be functionally connected to its host gene, TP63, especially ΔNp63, in cervical cancer." (PMID 32764455, 2020). "Additional DEGs that were overexpressed in cluster 8 included several known canonical cervical cancer oncogenes – CDKN2A, SERPINB3, TP63, and KRT5." (PMID 41362277, 2026). "Recent studies have reported that the most frequent integration sites of HPV were in the MACROD2, MIPOL1/TTC6, TP63, ERBB2, KLF12, and RAD51B gene by next-generation sequencing (NGS) in 272 Cervical cancer patients from the BioRAIDs study [NCT02428842]." (PMID 34680987, 2021). "KRT17 (CK17), TP63 and CDK2A (P16), markers of HPV target cells/cervical cancer stem cells (CSCs), were apparently upregulated in CIN and SCC." (PMID 34257574, 2021). "The aberrant expression of many mRNAs, including FGFR3, CTGF, TP63, IL36G, ADH7, SPINK5, and so on, have also been identified in cervical cancer." (PMID 32123519, 2020).
cervical cancer (continued). "In addition, ACTL6A co-expressed several important genes in the cervical cancer 3q amplicon, including PIK3CA, SOX2 and TP63." (PMID 34395295, 2021).
Ectrodactyly (15 papers, 2012 to 2025). A condition in which middle parts of the hands and/or feet (digits and meta-carpals and -tarsals) are missing giving a cleft appearance. "Pathogenic variants in the transcription factor TP63 are associated with clinically overlapping syndromes including ectrodactyly-ectodermal dysplasia clefting (EEC) and ankyloblepharon-ectodermal defects-cleft lip/palate (AEC)." (PMID 39364398, 2024). "Ectrodactyly‐ectodermal dysplasia‐clefting syndrome 3 (EEC) is one of the six overlapping syndromes caused by mutations in the tumor protein p63 gene (TP63)." (PMID 32881366, 2020). "Our study has identified a previously unknown mutation in TP63, a gene known to be associated with both oral clefts and ectrodactyly." (PMID 37070724, 2023). "Mutations in TP63 and WNT10B have been associated with ectrodactyly, and other regions of the genome have been mapped as containing some still unidentified causal genes." (PMID 37070724, 2023). "A possible diagnosis of Ectrodactyly-ED-Clefting (EEC), Rapp Hodgkin ((MIM 129400) or a related syndrome was also ruled out by our failure to find any disease-associated mutation in PCR amplified genomic DNA for analysis of TP63 (p63; TP73L) exons 5–8 and 13–14, and their flanking splice sites." (PMID 31125343, 2019).
head and neck squamous cell carcinoma (15 papers, 2016 to 2025). A squamous cell carcinoma that arises from any of the following anatomic sites: lip and oral cavity, nasal cavity, paranasal sinuses, pharynx, larynx, and salivary glands. "For example, TP63 has been implicated as an oncogene in several SC types, including head and neck squamous cell carcinoma (HNSC), LUSC, and ESSC." (PMID 35227282, 2022). "TP63 is also a prognostic marker as its loss is associated with metastatic progression in head and neck squamous cell carcinoma (HNSCC)." (PMID 36970727, 2022). "In murine model, TP63 loss led to activation of MAPK-P-STAT3 (Ser727)-MMP15 axis, resulting in metastatic spread of head and neck squamous cell carcinoma." (PMID 36936274, 2022). "ACTL6A was also found to interact with TP63 and regulate transcription of various key genes in head and neck squamous cell carcinoma (HNSCC), including a Hippo signaling pathway regulator WWC117." (PMID 29725063, 2018). "For instance, KLF7 binds to the IGF2BP2-SE to drive IGF2BP2 overexpression and promote tumor progression in head and neck squamous cell carcinoma (HNSCC), while TP63 and SOX2 co-activate SEs and the promoter of CCAT1 to drive tumorigenesis in squamous cell carcinomas (SCCs)." (PMID 41462308, 2025). "In tumor-related studies, such as in Head and Neck Squamous Cell Carcinoma (HNSCC) cells, the TP63 C-terminal TID domain was found to inhibit apoptosis and promote tumor progression." (PMID 38528613, 2024). "The transcription factor TP63 binds to the SEs region where LINC01503 is located to enhance its transcription and facilitate the invasion and metastasis of head and neck squamous cell carcinoma." (PMID 37658588, 2023). "We also analyzed TP63 and TDP‐43 expression levels in three other types of SCCs from TCGA, including lung squamous cell carcinoma (LUSC), cervical squamous cell carcinoma (CESC), and head and neck squamous cell carcinoma (HNSCC)." (PMID 39023169, 2024). "In this study, analysis of transcriptome data from The Cancer Genome Atlas (TCGA) demonstrated that expression of TP63 mRNA, particularly ΔNp63 isoforms, and HRAS are significantly elevated in advanced squamous cell carcinomas of the head and neck (HNSCCs), suggesting pathological significance." (PMID 37638000, 2023). "In addition to recurrent integrations in RAD51B, NR4A2, and TP63, additional genomic alterations were found in receptor tyrosine kinases, primarily FGFR2 and FGFR3, in HPV-positive head and neck squamous cell carcinoma." (PMID 27154171, 2016).
orofacial cleft (15 papers, 2012 to 2025). A disorder of facial skeleton that is characterized by cleft lip and/or cleft palate that result in feeding, speech and hearing problems caused by failures during development. "Disease-causing variants in TP63 are a known cause of birth defects with incomplete penetrance, including hydronephrosis, urethral stenosis, and orofacial clefts." (PMID 38654924, 2024). "A novel de novo mutation in the TP63 gene was found in a patient with an orofacial cleft and ectrodactyly." (PMID 37070724, 2023). "However, other TP63 variants have been described to cause forms of orofacial clefts including cleft lip, cleft palate and cleft uvula." (PMID 34629465, 2022). "Given the constellation of ectrodactyly, ectodermal features, and orofacial clefting, a TP63-related disorder (EEC syndrome) was suspected." (PMID 41141084, 2025). "Mouse knockouts of Acan,Dhrs3, Kmt2d, Recql4, Shh and Tp63 showed orofacial cleft phenotypes." (PMID 35817949, 2022). "Furthermore, TP63 has been implicated in human NSCL/P, and null mice recapitulate the human orofacial clefting phenotypes." (PMID 23028347, 2012). "It is possible that the orofacial cleft may have another etiology since the patient's uncle also had an oral cleft independent of the de novo TP63 mutation seen here." (PMID 37070724, 2023). "Interestingly, in Genome-wide meta-analyses of non-syndromic orofacial clefts an association was also found between SNPs located in a TP63 enhancer and clefts of the lip with or without cleft palate (CL/P)." (PMID 29311971, 2017). "Whole exome sequencing (WES) revealed a de novo heterozygous pathogenic variant in the TP63 gene: p.His247Arg: c.740A>G (NM_003722.4), which has been reported with ectrodactyly‐ectodermal dysplasia‐clefting syndrome 3 (EEC), both with and without orofacial clefting." (PMID 32881366, 2020).
EEC syndrome (14 papers, 2011 to 2025). EEC syndrome is a genetic developmental disorder characterized by ectrodactyly, ectodermal dysplasia, and orofacial clefts (cleft lip/palate). "Genetic testing revealed a heterozygous TP63 missense variant, c.740A>G (p.His247Arg), inherited from his affected father, confirming Ectrodactyly-Ectodermal Dysplasia-Clefting (EEC) syndrome." (PMID 41141084, 2025). "This case illustrates a classic presentation consistent with EEC syndrome, with additional urinary tract involvement, one of several developmental syndromes caused by mutations in TP63." (PMID 41141084, 2025). "This case contributes to the understanding of the EEC syndrome by documenting the clinical course of a child with a heterozygous TP63 (p.His247Arg) mutation inherited from his affected father." (PMID 41141084, 2025). "Mutation of the TP63 gene is responsible for 93% of SHFM cases associated with EEC syndrome; however, the exact pathogenesis causing the disrupted phenotype of normal hands and feet is still unclear." (PMID 39134968, 2024). "A de novo missense mutation of R304W in the TP63 gene is confirmed by whole-exome sequencing associated with EEC syndrome." (PMID 36386837, 2022). "At least 6 different syndromes have been linked to TP63 mutations, including EEC syndrome, ADULT syndrome, LMS, AEC syndrome, RHS, and SHFM." (PMID 33126320, 2020). "Mutations of TP63 are associated with various developmental disorders, including ectrodactyly–ectodermal dysplasia–cleftlip/palate (EEC) syndrome, ankyloblepharon–ectodermal defects–cleft lip/palate (AEC) syndrome and split-hand/foot malformation-IV syndrome." (PMID 32447427, 2020). "In some patients where the EEC syndrome was caused by mutations in TP63, the primary dentition was normal." (PMID 29311971, 2017). "The genetic defect was mapped to the subtelomeric region of chromosome 3q, which led to the identification of causative TP63 mutations in EEC syndrome, and subsequently related conditions including LMS." (PMID 27699475, 2016). "As basal and suprabasal cells of the PGCG epithelium show consistent p63 immunohistochemical reactions, mutation of the Tp63 gene may be responsible for the occurrence of PGCG in the patient suffering from EEC syndrome, as it was in the present case." (PMID 39134968, 2024). "Heterozygous mutations in TP63 are linked to several congenital syndromes, such as Ectrodactyly–Ectodermal Dysplasia–Cleft lip/palate (EEC) syndrome, Ankyloblepharon-Ectodermal Dysplasia-Clefting (AEC) syndrome, and others, which affect the development of epithelial tissues and structures." (PMID 39409174, 2024). "The confirmation of EEC syndrome can be done by molecular genetic testing for TP63 gene mutations." (PMID 26137453, 2015). "This mutation has been previously associated with Ectrodactyly–Ectodermal Dysplasia–Cleft lip/palate syndrome (EEC) syndrome and shown to reduce the transactivation activity of TP63 in a dominant-negative manner." (PMID 39409174, 2024). "Ectrodactyly-Ectodermal dysplasia-cleft (EEC) syndrome (MIM#604292) is a rare genetic disease caused by heterozygous, missense mutations in the TP63 gene." (PMID 36766837, 2023). "The concept of ELA syndrome, which is the original concept of combining 3 syndromes (EEC syndrome/LMS/ADULT syndrome) into a unique clinical entity, can help clinicians to better understand TP63-related syndromes and improve the differential diagnosis of these syndromes." (PMID 33126320, 2020).
esophageal squamous cell carcinoma (14 papers, 2018 to 2024). Esophageal squamous cell carcinoma (ESCC) is a type of esophageal carcinoma (EC) that can affect any part of the esophagus, but is usually located in the upper or middle third. "For instance, TP63 has been shown to promote the proliferation of esophageal squamous cell carcinoma (ESCC) cells by binding to the enhancer on the LINC01503 motif." (PMID 38933706, 2024). "The transcription of lncRNA LINC01503 was activated by TF TP63, resulting in shorter survival times for patients with esophageal squamous cell carcinoma." (PMID 34211553, 2021). "A clustered abnormality in copy number was observed in several genes, including CCND1 and SOX2 and/or TP63, in esophageal SCC, whereas a more widespread genomic instability and total DNA copy number alterations were observed in esophageal ADC." (PMID 33748520, 2018). "Whether SOX2 and ACTL6A/TP63 interact with the Hippo‐YAP1 pathway in esophageal squamous cell carcinoma (ESCC) remains unclear." (PMID 31560173, 2019). "The TF TP63 binds to the SE region upstream of LINC01503 in esophageal squamous cell carcinoma (ESCC) and activates it." (PMID 33042269, 2020). "Similarly, CRISPR-Cas9-mediated deletion of individual components of the TP63 SEs reduces its expression levels and restrains the proliferation of esophageal squamous cell carcinoma (ESCC) cells, unveiling the oncogenesis role of TP63 in tumor malignancy." (PMID 38844984, 2024). "The TP63/SOX2/CCAT1 complex activates EGFR, which activates its downstream signaling pathways in esophageal SCC." (PMID 32164712, 2020). "For example, the transcription factors, tumor protein p63 (TP63) and SRY-box transcription factor 2 (SOX2), which co-bind to the promoter and super-enhancer regions of the lncRNA CCAT1, regulate lineage-specific expression patterns in esophageal SCC." (PMID 32164712, 2020). "For example, the SEs of TP63, a lineage-specific master TF, are co-occupied with other CRC TFs (SOX2, KLF5, and TP63), and three SE constituents are required to transcribe TP63 as well as induce esophageal squamous cell carcinoma (ESCC) progression." (PMID 37501079, 2023).
melanoma (14 papers, 2010 to 2025). A malignant, usually aggressive tumor composed of atypical, neoplastic melanocytes. "ZBTB7A is known to promote metastasis in melanoma and TP63 is associated with resistance to therapeutic agents." (PMID 28472408, 2017). "In particular, downregulation of ZBTB7A or TP63 has already been associated with poor prognosis of melanoma patients." (PMID 28472408, 2017). "It is clear that the the role of loss of expression of TP63 in melanoma warrants further investigation." (PMID 20805891, 2010). "Furthermore, unexpected evidence recently emerged of a high incidence of mutation in the TP63 gene in melanoma samples (14.7% of samples)." (PMID 31744230, 2019). "All normal skin samples, as well as nevi and a couple of primary melanomas have relatively low values of ADA but they express TP63." (PMID 20805891, 2010). "There is a change of roles in metastatic and some primary melanomas, which have reduced TP63 expression but increased values of expression of ADA." (PMID 20805891, 2010).
ADULT syndrome (13 papers, 2011 to 2025). "In sharing this case, we aim to contribute to the current understanding of the genes and clinical manifestations of ADULT syndrome and to assist clinicians in the clinical diagnosis of TP63 mutation-related diseases." (PMID 37920856, 2023). "Ectrodactyly ectodermal dysplasia-cleft lip/palate (EEC) syndrome, limb-mammary syndrome (LMS), and acro-dermato-ungual-lacrimal-tooth (ADULT) syndrome are caused by a TP63 gene disorder and have similar features." (PMID 33126320, 2020). "The ADULT syndrome is also caused by TP63 mutations in the germline." (PMID 39791744, 2025). "Interestingly, a case report described a patient with ADULT syndrome-like phenotype associated with CP and TA, who was found to be heterozygous for a de novo mutation in TP63." (PMID 27699475, 2016). "Recently, a case series on TP63-associated POI showed that same variant may cause POI or isolated cleft palate in relatives, but also that non-syndromic POI may be caused by variant associated with ADULT syndrome, which makes the resulting phenotype prediction uncertain." (PMID 41393291, 2025).
lung adenocarcinoma (13 papers, 2016 to 2025). A carcinoma that arises from the lung and is characterized by the presence of malignant glandular epithelial cells. "Variation in TP63 is associated with lung-adenocarcinoma (AC) susceptibility in Japanese and Korean populations." (PMID 35584089, 2022). "We found a significant positive correlation between the expression of miR-205-5p and both isoforms of TP63 in lung adenocarcinoma (LUAD) datasets." (PMID 40181048, 2025). "In fact, our study demonstrates a collaboration between short and long TP63 isoforms in controlling migration in lung adenocarcinoma cells." (PMID 40181048, 2025). "On the other hand, although TP63 amplification and expression has been reported in a small subset of lung adenocarcinoma, the biological mechanisms under the role of TP63 remain unclear." (PMID 34552866, 2021). "Four loci, 5p15.33 (TERT), 6p21.3 (BTNL2), 3q28 (TP63) and 17q24.2 (BPTF), previously shown to be strongly associated with overall lung adenocarcinoma risk in East Asians, were re-discovered as loci associated with a higher susceptibility to EGFR mutation-positive lung adenocarcinoma." (PMID 27501781, 2016). "It has been observed that the TP63 gene is amplified in 88% of lung squamous carcinoma (LUSC) cases and in 11% of lung adenocarcinoma (LUAD) cases." (PMID 40181048, 2025). "By analyzing gene expression signatures of AK family in TCGA lung adenocarcinomas, we surprisingly found that target genes of “SCC” marker p63 (TP63) were increasingly upregulated upon the over-expression of AK4 and the under-expression of AK1." (PMID 31444368, 2019). "Some groups of cells expressing NAPSA and negative for TP63 were identified as lung adenocarcinoma cells." (PMID 32854746, 2020).